IGKV3D-11 (immunoglobulin kappa variable 3D-11)
Description:
V region of the variable domain of immunoglobulin light chains that participates in the antigen recognition. Immunoglobulins, also known as antibodies, are membrane-bound or secreted glycoproteins produced by B lymphocytes. In the recognition phase of humoral immunity, the membrane-bound immunoglobulins serve as receptors which, upon binding of a specific antigen, trigger the clonal expansion and differentiation of B lymphocytes into immunoglobulins-secreting plasma cells. Secreted immunoglobulins mediate the effector phase of humoral immunity, which results in the elimination of bound antigens. The antigen binding site is formed by the variable domain of one heavy chain, together with that of its associated light chain. Thus, each immunoglobulin has two antigen binding sites with remarkable affinity for a particular antigen. The variable domains are assembled by a process called V-(D)-J rearrangement and can then be subjected to somatic hypermutations which, after exposure to antigen and selection, allow affinity maturation for a particular antigen.
Synonyms: IGKV3D11; L20
Gene: Immunoglobulin variable (V) gene on chromosome 2 (90,172,802 to 90,173,414, forward strand). Ensembl gene ENSG00000211632.
Subcellular location: Secreted; Cell membrane
Subcellular location (Human Protein Atlas): Cytosol; Plasma membrane; Predicted to be secreted
Gene Ontology:
Biological process: immune response
Cellular component: extracellular region; immunoglobulin complex; plasma membrane
Homologues: Orthologues: mouse Igkv18-36 (69% identical), rat Igkvl13 (66% identical). Paralogues in human: IGKV3-11 (98% identical), IGKV3OR2-268 (91% identical), IGKV3-15 (90% identical), IGKV3-20 (90% identical), IGKV3D-20 (90% identical), IGKV3D-15 (89% identical), IGKV3-7 (88% identical), IGKV3D-7 (86% identical), IGKV1D-13 (70% identical), IGKV1-9 (69% identical), IGKV1-39 (68% identical), IGKV1-5 (68% identical), and 81 more.